APOE (apolipoprotein E)
Diseases named in the same sentence as APOE in open-access papers (continued):
Sharing a sentence is not in itself a finding about the gene and the disease.
Hypertension (continued). "Some cohorts also controlled for other conventional risk factors, including BMI, APOE status, hypertension and cardiovascular disease." (PMID 35202496, 2022). "Differences in the level of education, hypertension, and APOE polymorphism were observed between the fluoride group and the control group." (PMID 34886821, 2021). "The AD group was older than the normal control group (p < 0.05) and had more frequent hypertension and APOE e4 allele than the controls (p > 0.05)." (PMID 34829528, 2021). "The APOE ε4 allele and the genotypes (ε3/ε4 and ε4/ε4) were associated with an increased risk of hypertension in different population studies, for example, in Asians and Caucasians." (PMID 34828374, 2021). "Our results also indicated that hypertension is the major independent risk factor for IS and has a significant impact than ApoE gene polymorphism on IS development." (PMID 33833872, 2021). "The T2D group had significantly higher proportions of smokers, hypertension, and dyslipidemia; significantly lower proportions of females and ApoE ε4 allele carriers; and significantly shorter education periods compared with the control group." (PMID 34660814, 2021). "Studies have shown that myocardial hypertrophy due to peripheral vascular resistance, hypertension and endothelial dysfunction 26, myocardial fibrosis, and reduced cardiac functional reserve cause cardiac dysfunction in apolipoprotein E-knockout mice." (PMID 34394711, 2021). "Next, we examined differences in risk factors of hypertension according to APOE polymorphism (rs7412), which has the highest beta value in the GLGC (Assumption 2)." (PMID 33637130, 2021). "In our GWAS, genes related to blood pressure (NLRP6, CREB5 and APOE) were found in regions associated with mtDNA abundance, providing a potential explanation between increased mtDNA abundance and reduced risk for hypertensive diseases." (PMID 33385171, 2021). "Multiple vascular risk factors are associated with CAA, including aging, ApoE-ε4 genotype, cerebrovascular disease, hyperlipidemia, and hypertension." (PMID 33329053, 2020). "Immunohistochemistry for ApoE revealed positive stains in the vascular wall in association with increased wall thickness due to high blood pressure in systemic hypertension patients who died of ischemic stroke." (PMID 33348552, 2020). "Association of ApoE polymorphisms with prevalent hypertension in 1406 older adults: the Bambuí Health Aging Study (BHAS)." (PMID 32876203, 2020). "Is history of hypertension and apolipoprotein E (APOE) associated with intracerebral hemorrhage risk in participants stratified by self-reported race/ethnicity?" (PMID 30726504, 2019). "It is noteworthy that a significant amount of amyloid burden has been detected in [18F]FBP scans among even cognitively normal elderly patients who have uncontrolled hypertension and underlying risk factors such as the presence of one or more APOE ε4 alleles." (PMID 31242587, 2019). "There was evidence of supra-multiplicative interaction between the presence of an APOE e4 allele and untreated hypertension on several cognitive assessments (p = 0.02 for the TICS; p = 0.045 for global composite score; p<0.01 for working memory)." (PMID 31697783, 2019). "Because these analyses revealed substantial heterogeneity by race/ethnicity, we further explored the degree to which the differential burden of hypertension across populations is associated with the variability in observed APOE risks." (PMID 30726504, 2019). "Among haemorrhage survivors with hypertension (stage 1 and beyond) APOE genotype also stratified risk for all small vessel disease outcomes." (PMID 32954261, 2019). "The coexistence of APOE ε4 and hypertension was associated with worse cognitive function compared to those with neither or either alone." (PMID 30866553, 2019).
Hypertension (continued). "After propensity score matching for hypertension burden, APOE ε4 was associated with lobar ICH risk among Hispanic (OR, 1.14; 95% CI, 1.03-1.28; P = .01) but not in black (OR, 1.02; 95% CI, 0.98-1.07; P = .25) participants." (PMID 30726504, 2019). "A propensity score analysis was used to model the association of APOE with the burden of hypertension across race/ethnic groups." (PMID 30726504, 2019). "We also tested for interaction between APOE e4 allele carrier status and hypertension overall, as well as for apparently untreated and treated hypertension." (PMID 31697783, 2019). "We used a PS analysis to attempt to isolate the association of APOE against the imbalanced burden of hypertension across race/ethnicity." (PMID 30726504, 2019). "The main risk factors associated with AD in Iranian population are age, ApoE allele, depression and hypertension." (PMID 31993381, 2019). "In conclusion, APOE genotype modifies the already strong association of hypertension with multiple small vessel disease clinical outcomes among intracerebral haemorrhage survivors." (PMID 32954261, 2019). "Specifically, it has been found that apolipoprotein E polymorphism influences the effect of alcohol on hypertension, conferring more or less proneness to blood pressure increase depending on the allele carried." (PMID 30728434, 2019). "Age, ApoE allele, depression and hypertension were identified as the main risk factors associated with this disease in Iran, in this systematic review." (PMID 31993381, 2019). "The role of apolipoprotein E (ApoE) polymorphism in PE was proposed based on PE-like features, such as hypertension, proteinuria, and increased expression of sFlt-1, detected in the ApoE knockout mice." (PMID 31817906, 2019). "These associations survived adjustments for age, sex, education, APOE*ε4, smoking history, cardiovascular disease history, hypertension history, BMI and corrections for multiple testing." (PMID 29860628, 2018). "Individuals in the hypertension group with APOE ε4 allele, specifically in the high vascular risk group, showed significantly greater levels of Aβ deposition than individuals with a single VRF or none at all." (PMID 29867442, 2018). "When combined with traditional risk factors, P1 was mostly affected by dyslipidemia, smoking and hypertension, while P2 was mostly affected by their fasting blood sugar levels and ApoE variant." (PMID 28086795, 2017). "ApoC-II, apoC-III, and apoE were associated with obesity, hypertension, impaired glucose metabolism, and most strongly with lipid parameters, particularly, CEs and TAGs with shorter and more saturated fatty acid chains." (PMID 28209220, 2017). "In contrast to risk factors such as APOE ε4 status and hypertension, protective factors such as education have also been suggested to impact cognitive functioning in aging." (PMID 29375362, 2017). "As noted, KIBRA, APOE, and hypertension have all been implicated in episodic memory functioning and hippocampal volumes." (PMID 29375362, 2017). "A case-control study in Russia found that intracranial aneurysms with hypertension were associated with the e2 allele and the e2/e3 APOE genotype." (PMID 26830841, 2016). "The vast majority of cases occur sporadically and a large series of risk factors have been identified, including age, type 2 diabetes, high blood pressure, and various genetic factors like specific alleles of apolipoprotein E (APOE)." (PMID 27566602, 2016). "Evidence from a meta-analysis of 45 studies found that APOE gene polymorphisms were associated with essential hypertension." (PMID 26830841, 2016). "Other known risk factors include family history, hypertension and hypotension, high cholesterol levels, low levels of physical activity and of education, obesity, and the presence of epsilon 4 alle of the apolipoprotein E gene (APOE4)." (PMID 25041352, 2015).
Hypertension (continued). "Cases had significantly fewer years of education; higher frequency of type 2 diabetes, hypertension, coronary artery disease, depressive symptoms, and APOE ε4 allele status; and marginally higher PP levels compared to controls (P = 0.073)." (PMID 26441635, 2015). "In contrast, WMH microbleeds visualized on T2*-weighted MRI scans were linked to arterial hypertension as well as to low levels of CSF Aβ1–42 and homozygosity for the APOE ε4 allele." (PMID 25984242, 2015). "The observed effects of APOE risk allele as well as hypertension on WMH volume emphasize the importance of attending to microvascular pathology in AD, which so far has frequently been an exclusion criterion in AD studies." (PMID 25984242, 2015). "A meta-analysis showed that the APOE ε4 allele was associated with an increased risk of developing hypertension." (PMID 24621278, 2014). "This raises the possibility that severe hypertension or cardiovascular disease, as would be predicted by a dual state of elastin insufficiency and ApoE deficiency, can cause predisposition to metabolic dysfunction." (PMID 26167199, 2014). "A meta-analysis of 45 studies including 13,940 cases and 16,364 controls found that APOE gene polymorphisms were associated with essential hypertension." (PMID 24456740, 2014). "In humans with mild cognitive impairment and AD, the APOE ε4 allele was associated with higher risk of cerebral cortex microbleeds in men than in women, although that was also dependent on other risk factors, such as hypertension, diabetes, and age." (PMID 41035821, 2025). "In addition to APOE’s involvement in lipid metabolism, APOE4 is associated with hypertension and obesity, both of which are risk factors for CVD and T2DM." (PMID 39364911, 2025). "However, risk factors for ARIA include APOE ε4 carriership and hypertension, which are key risk factors for CAA and arteriolosclerosis, respectively." (PMID 41379352, 2025). "This is particularly relevant given APOE’s established roles in lipid metabolism and vascular function, which could independently influence hypertension risk." (PMID 41008513, 2025). "Moreover, the established risk factors for ePVS were also widely described, including advancing age, hypertension, and genetic susceptibility, such as the apolipoprotein E (APOE)-ε4 allele." (PMID 40943799, 2025). "Associations were stronger among APOE ε4 carriers and heavy drinkers, and may be partly explained by depression, hypertension and ischaemic heart disease." (PMID 41275373, 2025). "Hypertension and apolipoprotein E (APOE) ε4 are risk factors for CAA." (PMID 41057989, 2025). "Hypertension was linked to higher costs, as were a positive APOE e4 or Aß status." (PMID 40571933, 2025). "It is important to note that our results did not diminish substantially after controlling for common vascular health risk factors, such as hypertension status, high cholesterol status, smoking history, BMI, and cardiorespiratory fitness levels, as well as APOE ε4 status, and further depressed mood." (PMID 40436879, 2025). "In addition, significant risk factors related to the CIMT-WMH association included older age, hypertension, depression, migraine, Hispanic ethnicity, and apolipoprotein E (ɛ4) in postmenopausal women." (PMID 38903057, 2024). "Hypertension leads to cerebrovascular disease and brain damage, whereas APOE ε4 gene expression may cause neuronal damage and inflammatory responses." (PMID 38062190, 2023). "In summary, the APOE rs7412T/T genotype may be a risk factor for hypertension in the Chinese Hakka population." (PMID 36158751, 2022). "In the same way, the APOE rs7412T/T genotype in the co-dominant mode (T/T vs. C/C) (adjusted OR 2.682, 95% CI 1.072–6.710, P=0.035) was a significant risk factor for hypertension, while the MTHFR rs1801133 polymorphism in these genetic modes was not a significant risk factor for hypertension." (PMID 36158751, 2022).
Hypertension (continued). "Based on these previous findings, we could infer the existence of the joint effect of the APOE risk gene and hypertension on the functional connectivity (FC) of RSNs." (PMID 35624902, 2022). "APOE + 2836G>A polymorphism is associated with the susceptibility to hypertension." (PMID 36158751, 2022). "We hypothesized that the hypertension patients with APOE ε4 carrier would be associated with changed functional connectivity of frontoparietal networks, leading to deficits in cognitive functions." (PMID 35624902, 2022). "The APOE rs7412T/T genotype was found to be a risk factor for hypertension in this study." (PMID 36158751, 2022). "It provides evidence that APOE gene polymorphisms are linked to hypertension." (PMID 36158751, 2022). "For apolipoproteins, apoA1 and apoE polymorphism were closely associated with hypertension." (PMID 36551995, 2022). "It supports that APOE polymorphisms are related to hypertension in the Hakka population." (PMID 36158751, 2022). "The APOE rs7412T/T genotype in the co-dominant model (APOE rs7412T/T vs. C/C) (gender-, age-, smoking-, and drinking-adjusted OR 2.682, 95% CI, 1.072–6.710, P=0.035) was a significant risk factor for hypertension." (PMID 36158751, 2022). "Results showed that APOE-ε4 allele carriers had lower cerebral blood flow, and the effects of this on cognitive performance (Trail Making Test and the Hopkins Verbal Learning Test) were made worse by the co-occurrence of hypertension." (PMID 36324708, 2021). "In addition, C-carriers of Clock Circadian Regulator (Clock) T3111C polymorphism who had hypertension and APOE ε4 carriers with dyslipidemia had a higher risk of conversion to AD." (PMID 33352859, 2020). "Parental history of early-onset dementia (β = 21.30 [95% CI, 15.01 to 27.59]), presence of 1 APOE ε4 allele (β = 5.00 [95% CI, 2.11 to 7.88]), and history of hypertension (β = 3.81 [95% CI, 0.88 to 6.74]) were associated with later-than-expected intergenerational difference in AAO of AD." (PMID 31617930, 2019). "This review article will highlight the molecular mechanisms by which peri-menopause may influence the female brain vulnerability to AD and AD risk factors, such as hypertension and apolipoprotein E (APOE) genotype." (PMID 31551757, 2019). "In this case-control study of 13 124 adults, having a copy of APOE ε4 alleles increased the risk for lobar intracerebral hemorrhage only in white individuals, but after propensity score matching for hypertension burden, Hispanic individuals showed the same risk of APOE ε4." (PMID 30726504, 2019). "While treatment of hypertension is a universal recommendation, treatment of hypertension may be particularly important among carriers of the APOE e4 allele, and can provide a rationale for more widespread testing for the APOE e4 allele." (PMID 31697783, 2019). "On the other hand, representing the remaining 97%, the late onset form of AD (LOAD) which is associated with advanced age, mutations of the apolipoprotein E (APOE) ε4 allele, hypertension and hyperlipidaemia, as well as with coronary disease, T2DM and obesity among other less determinant factors." (PMID 31551756, 2019). "Women with hypertension and at least one APOE e4 allele had worse average cognitive function compared with women without hypertension with the e3/3 genotype; this difference was amplified among APOE e4 allele carriers with untreated hypertension." (PMID 31697783, 2019). "apolipoprotein E (APOE) is associated with sleep apnea in a context-dependent manner, with the association stronger in younger individuals, and those with cardiovascular disease or hypertension." (PMID 23617951, 2013). "Type 2 diabetes interacts with aging,hypertension, Ab deposition, and the APOE 4 allele." (PMID 29213654, 2010). "Additionally, the peak on chromosome 19 (BMI slope) is near the ApoE locus, which has previously been associated with risk for hypertension and CVD." (PMID 14975113, 2003).
Hypertension (continued). "In addition, significant risk factors related to the CIMT-WMH association included older age, migraine and depressed patients with WMH (Kocatürk and Kocatürk, 2020), hypertension, Hispanic ethnicity, and the presence of apolipoprotein E (APOE) ɛ4 allele in postmenopausal women." (PMID 38903057, 2024). "To test this hypothesis, we used apolipoprotein E deficient (ApoE–/–) mice with adipose tissue BMP4 knockout or brown adipose tissue BMP4 knockout to examine effects of impaired PVAT metabolism on the development of hypertension." (PMID 36457800, 2022). "Specifically, the APOE rs7412T/T genotype may be a risk factor for hypertension." (PMID 36158751, 2022). "Our findings are clinically relevant, given the modifiable nature of many cardiovascular risk factors such as smoking and high blood pressure, and may contribute to our understanding of the observed heightened susceptibility to tauopathy among female APOE ɛ4 carriers." (PMID 35233525, 2022). "In addition, few studies have examined whether antihypertensive medication use influences the association between hypertension and APOE e4 genotype on late-life cognitive function." (PMID 31697783, 2019). "Furthermore, APOE ε4 allele was also associated with an increased risk of developing hypertension, which may be the reason that APOE ε4 allele was associated with a higher risk of ICH." (PMID 24621278, 2014). "We correlated ≈11K transcripts with APOE genotypes using standard linear regression adjusted by sex, and medication for hypertension, type 2 diabetes, high cholesterol, and heart disease." (PMID 41316897, 2026). "Partial correlation analysis, adjusting for potential confounders including age, sex, education level, MNA‐SF score, history of hypertension and APOE genotype, confirmed the positive correlation between TMT and MoCA‐B (r = 0.124, p = 0.001)." (PMID 40717521, 2025). "In the MCI population, males and females differed in years of education, prevalence of hypertension, tau load, and carrier prevalence for APOE ε4." (PMID 40289834, 2025). "Risk factors for AD, such as a high‐fat diet, female gender, the APOE gene, sedentary lifestyle, hypertension, and aging, are known to induce the production of OPN." (PMID 39957678, 2025). "While systemic proteomic changes were consistent across APOE ε4 carriers, their relationship with clinical and lifestyle factors, such as hypertension and smoking, varied by disease." (PMID 40665049, 2025). "Linear regression models were used to examine baseline hypertension, body mass index (BMI), long-term glucose levels (HbA1c), different lipid levels, physical activity, alcohol consumption, smoking, education, APOE genotype, age and sex." (PMID 38926747, 2024). "Our analysis revealed that facial nerve angel, hypertension, APOE ε4 genotype, and brainstem compression were shown to be associated with the rate of progression of hemifacial spasm in univariate analysis." (PMID 38606273, 2024). "The apolipoprotein E genotype, age and ethnicity showed a three-way interaction with the brain age index (ɛ4 carriers × hypertension × ethnicity, β=1.091, P = 0.014)." (PMID 39007039, 2024). "We performed lipidomic analyses on plasma collected from mice (control, hyperlipidemia [ApoE-/- group], heart failure with hyperlipidemia, and hypertension [ApoE-/- with angiotensin II group])." (PMID 39198543, 2024). "Participants with hypertension and APOE-ε4 had higher age-residualized PVS and microbleeds, respectively." (PMID 38811657, 2024). "Higher numbers of NPS and more severe NPS were also tied to lower cognitive performance beyond age, education, arterial hypertension, AD pathology and APOE status." (PMID 39232823, 2024). "In the final model, after the addition of three covariates, arterial hypertension in the second, AD pathology in the third, and APOE status in the fourth step, the variance explained increased to 14% (pseudo R2) or remained at 24% (adjusted R2)." (PMID 39232823, 2024).